ENSG00000259697 (novel transcript)
Synonyms: LOC107984784
Gene: Long non-coding RNA gene on chromosome 15 (62,193,542 to 62,222,911, reverse strand). Ensembl gene ENSG00000259697.
Gene Ontology:
Molecular function: pre-mRNA branch point binding
Biological process: mRNA branch site recognition
Cellular component: U2 snRNP